ENSG00000267477 (novel protein)
Gene: Protein-coding gene on chromosome 19 (11,466,240 to 11,505,698, reverse strand). Ensembl gene ENSG00000267477.
Genetic constraint (gnomAD): Missense variants: 253 observed, 242.52 expected, observed/expected ratio (o/e) 1.04, 90% interval 0.94 to 1.16. Synonymous variants: 144 observed, 107.11 expected, observed/expected ratio (o/e) 1.34, 90% interval 1.17 to 1.54.